ZNF470 (zinc finger protein 470)
Description:
May be involved in transcriptional regulation.
Synonyms: CZF-1; FLJ26175
Tractability: PROTAC: ubiquitination databases record sites on it.
Gene: Protein-coding gene on chromosome 19 (56,567,468 to 56,588,911, forward strand). Ensembl gene ENSG00000197016.
Subcellular location: Nucleus
Subcellular location (Human Protein Atlas): Nuclear bodies; Nucleoplasm
Pathways (Reactome):
Gene expression (Transcription): Generic Transcription Pathway
Gene Ontology:
Molecular function: DNA-binding transcription factor activity, RNA polymerase II-specific; RNA polymerase II cis-regulatory region sequence-specific DNA binding
Biological process: regulation of transcription by RNA polymerase II; regulation of DNA-templated transcription
Cellular component: nuclear body; nucleoplasm; nucleus
Genetic constraint (gnomAD): Loss-of-function variants: 13 observed, 15.08 expected, observed/expected ratio (o/e) 0.86, 90% interval 0.56 to 1.37. The upper end of that interval is the gene's LOEUF score, 1.37, which puts it in group 5 of 6, group 1 being the genes least tolerant of losing a copy. Missense variants: 928 observed, 886.25 expected, observed/expected ratio (o/e) 1.05, 90% interval 0.99 to 1.11. Synonymous variants: 293 observed, 290.14 expected, observed/expected ratio (o/e) 1.01, 90% interval 0.92 to 1.11.
Homologues: Orthologues: chimpanzee ZNF470 (99% identical), macaque ZNF470 (91% identical), dog ZNF470 (90% identical), pig ZNF470 (88% identical), rabbit ZNF470 (86% identical), rat Zfp939 (34% identical). Paralogues in human: ZFP28 (56% identical), ZNF471 (55% identical), ZNF658 (45% identical), ZNF33B (43% identical), ZNF546 (42% identical), ZNF585B (42% identical), ZNF197 (41% identical), ZNF28 (41% identical), ZNF484 (41% identical), ZNF568 (41% identical), ZNF41 (41% identical), ZNF595 (40% identical), and 164 more.
Diseases named in the same sentence as ZNF470 in open-access papers:
ZNF470 is named in the same sentence as 2 diseases in open-access papers, as found by Europe PMC text mining. Sharing a sentence is not in itself a finding about the gene and the disease. The quoted sentences say what the papers report.
Obesity (1 paper, 2022). Accumulation of substantial excess body fat. "As a result, we found GWAS signals relevant to obesity around rs2870099 as follows: rs34863160 (ZNF470), rs11670527 (DUXA, ZNF264), and rs16987303 (ZNF471) were associated with birth weight, BMI, and height, respectively." (PMID 36276968, 2022).
ZNF470 also shares sentences with these, for which no sentence is quoted: infection (1 paper).